CRKL (CRK like proto-oncogene, adaptor protein)
Diseases named in the same sentence as CRKL in open-access papers (continued):
Sharing a sentence is not in itself a finding about the gene and the disease.
tumor (continued). "This review demonstrates that tumor cell migration and invasion are the two cellular functions that have been studied the most for the p130Cas-Crk/CrkL axis." (PMID 40362257, 2025). "Our results indicate that CRKL is a tumour promoter playing a vital role in the development and progression of CML." (PMID 38683131, 2024). "CRKL acts as tumour promotor and miR‐429 acts as a tumour suppressor in CML, their dysexpressions are involved in the carcinogenesis and progression of CML." (PMID 38683131, 2024). "CRKL has been proved to be an oncogene, which plays a role in promoting tumor invasion and metastasis in various tumors involved in immune escape and EMT." (PMID 38717531, 2024). "The overexpression of USP53 in TNBC promotes the deubiquitination of CRKL and tumor growth and metastasis in TNBC." (PMID 37894400, 2023). "According to PhosphoSitePlus29, CRKL pY207 is a known substrate of the tumor-driving fusion kinase BCR-ABL and can be regarded as a true responsive site of Dasatinib treatment." (PMID 38036588, 2023). "Overall, we discovered that USP53 deubiquitinates CRKL, encourages tumor development and metastasis, and reduces chemosensitivity in TNBC." (PMID 37894400, 2023). "In summary, we found that USP53 can deubiquitinate CRKL, thus regulating tumor proliferation, metastasis, and sensitivity to chemotherapy in TNBC." (PMID 37894400, 2023). "In hepatocarcinoma cells, miR-124-3p targets and degrades the CRKL mRNA through the miRNA-mediated gene silencing and suppresses the invasion and metastasis, thereby acting as a tumor suppressor miRNA." (PMID 35511336, 2022). "In gastric, miR-126 has been validated to extremely decreased and suppress tumor mobility through targeting multiple targets, like CRKL and SLC7A532,33." (PMID 36535956, 2022). "This review systematically analyzes the studies on the role of Crk and CrkL in tumor cell functions to gain perspective on distinct and overlapping functions of Crk and CrkL in cancer cells." (PMID 33801580, 2021). "Different authors reported direct and indirect correlation between BCL2 protein and STATs or CRKL in different tumor models, supporting, thus, our data." (PMID 34884309, 2021). "The contribution of Crk and CrkL to various tumor cell functions in vitro and in vivo has been studied extensively for the last two decades." (PMID 33801580, 2021). "The requirement of Crk or CrkL for cell proliferation in vitro, anchorage-independent cell growth, cell migration and invasion, in vivo tumor growth in mice, and metastasis has been demonstrated in multiple cancer cell lines." (PMID 33801580, 2021). "A comprehensive understanding of individual and overlapping roles of Crk and CrkL in tumor cell functions is necessary to develop effective therapeutic strategies." (PMID 33801580, 2021). "Because GBM is divided into several subtypes and is highly heterogeneous, further in vitro and in vivo studies using additional GBM cell lines and patient tumor tissues are needed to validate the overlapping functions of Crk and CrkL in GBM." (PMID 33561443, 2021). "This review systematically discusses crucial functions of Crk and CrkL in tumor cell functions and provides new perspectives on targeting Crk and CrkL in cancer therapy." (PMID 33801580, 2021). "In line with their contribution to in vitro cell proliferation and anchorage-independent cell growth, effects of Crk and CrkL on in vivo tumor growth have been studied using the gene knockdown or knockout approach." (PMID 33801580, 2021). "Previously, we found that CRKL was overexpressed in hepatocarcinoma patient tumour tissues and cells, indicating CRKL overexpression potentially e promoted hepatocarcinogenesis." (PMID 33523562, 2021). "Reduced expression of either Crk or CrkL by RNA interference-mediated gene knockdown has been shown to lead to inhibition of in vivo tumor growth of various cancer cell lines." (PMID 33801580, 2021).
tumor (continued). "As a member of the CRK (v‐crk sarcoma virus CT10 oncogene homologue) adapter protein family, CRKL (CRK‐like) associated with the development and progression of various tumours." (PMID 33523562, 2021). "All these results suggest that Crk and CrkL play critical roles in tumor cell migration and invasion in a variety of cancers." (PMID 33801580, 2021). "The effect of Crk and CrkL on tumor cell migration and invasion has also been studied using overexpression of Crk or CrkL in tumor cells." (PMID 33801580, 2021). "Overall, knockdown or knockout of Crk or CrkL suppressed tumor cell growth in vitro and in vivo, whereas overexpression of Crk or CrkL promoted tumor cell growth." (PMID 33801580, 2021). "The upregulations of ETV6 and CRKL were positively correlated in both hepatocarcinoma patients’ tumorous tissues (R2 = 0.4955, P = 0.0136) and in hepatocarcinoma cells (R2 = 0.9604, P = 0.0200)." (PMID 32326970, 2020). "In contrast, DKO and CrkL KO T cells were unable to clear the subcutaneous tumor and these recipients were sacrificed due to the resulting tumor pathology." (PMID 32391120, 2020). "WB assay showed CRKL expression was upregulated by 79.6% (P = 0.0041) in the tumorous tissues from hepatocarcinoma patients." (PMID 32326970, 2020). "We also observed a significant negative correlation between the expression levels of miR-429 and CRKL in hepatocarcinoma tumor tissues and hepatocarcinoma cell lines." (PMID 32326970, 2020). "Collectively, our data discloses that miR-124-3p acts as an important tumor-suppressive miRNA through targeting and regulating CRKL in HCC." (PMID 33094104, 2020). "Beside the physiological cytoplasmic expression, the analysis of LSCC tumor samples revealed also nuclear expression of CRKL protein in 10/40 (25%) cases, of which three (7.5%), presented moderate or strong nuclear expression." (PMID 31913340, 2020). "This analysis revealed the presence of cytoplasmic expression of CRKL protein in all 40/40 (100%) tumor samples." (PMID 31913340, 2020). "To establish the intensity and subcellular localization of CRKL protein in laryngeal squamous epithelium under physiological condition we performed immnunohistochemical staining using the non-tumor laryngeal squamous epithelium." (PMID 31913340, 2020). "Our results indicated that CRKL acts as a tumor promoter in hepatocarcinoma by promoting tumor cell’s aggressiveness." (PMID 32326970, 2020). "In the current study, the protein level of CRKL was upregulated by 79.6% (P = 0.0041) in the tumor from 16 additional hepatocarcinoma patients." (PMID 32326970, 2020). "CRKL was also upregulated in hepatocarcinoma patients’ tumorous tissues and hepatocarcinoma cell lines." (PMID 32326970, 2020). "Collectively, our data illustrates that miR-124-3p acts as an important tumor-suppressive miRNA to suppress HCC carcinogenesis through targeting CRKL." (PMID 33094104, 2020). "Previously, we detected that endogenous expression level of CRKL in the tumorous tissues from 12 hepatocarcinoma patients was upregulated by 66.7% compared to the paired non-tumor live tissues." (PMID 32326970, 2020). "To ask if CrkL is also the critical Crk family member responsible for T cell migration in vivo, we utilized a graft-versus-host/graft-versus-tumor mouse model (GvHD/GVT)." (PMID 32391120, 2020). "For this purpose, a paraffin-embedded cancer progression tissue microarray (TMA), containing 94 tumor cores, was immunostained for CrkL." (PMID 31323992, 2019). "These cell lines stem from disparate tumor or tissue types, but they were all predicted to have very high recruitment of CRKL (more than one copy of CRKL bound to each molecule of IGF1R) coupled with moderately high recruitment of either SRC, SHC1, or RASA1." (PMID 30653502, 2019). "It was proposed that unphosphorylated intracellular CrkL fraction is secreted from the tumor cells into the TME either through an active transport mechanism or as a result of cell death into the microenvironment." (PMID 31323992, 2019).
tumor (continued). "Intracellularly located CrkL binds to tyrosine kinase phosphorylated scaffold proteins, such as C3G, paxillin, and p130Cas, thus being involved in tumor cell adhesion and migration through integrin mediated signaling." (PMID 31323992, 2019). "It was showed that CRKL was upregulated in most tumor stages, with a significant upregulation was observed in the stage I samples." (PMID 31133010, 2019). "Cell proliferation in shRNA treatment group was declined when compared with the control, consistent with a possible role of CRKL gene in facilitating the proliferation of tumor cells." (PMID 31133010, 2019). "A recent study showed that the PI3K pathway in PTEN-null tumours that rely on p110β are regulated by the Crk-like protein (CRKL) adaptor protein." (PMID 30544563, 2018). "The linkages of Raf/MEK/ERK pathway and EMT to miR-429- and/or CRKL-mediated tumor migration and invasion were further validated using PD98059, a specific pERK1/2 inhibitor, for specific signaling blocking." (PMID 29403024, 2018). "Patients with high expression of either ABCG2 or CRKL in tumor tissue presented a significant tendency towards poor prognosis and high mortality (P < 0.05)." (PMID 28029654, 2017). "Data from multiple large tumor sets from The Cancer Genome Atlas (TCGA) reveals that CRKL expression is negatively correlated with miR-200 family expression, positively associated with ZEB1, EMT status, and Src signaling." (PMID 26728244, 2016). "Patients with high correlated expression of either CRKL or SLC7A5 in tumor tissue showed a significant tendency towards poor prognosis and high mortality (P<0.05)." (PMID 27846244, 2016). "In an expanded analysis of CRKL alterations across all tumor types, 99.5% were CRKL amplifications and 0.5% were CRKL base substitutions." (PMID 25897431, 2015). "The cooperative functions of p130Cas and Crk/CrkL have been reported in non-tumor cells." (PMID 40362257, 2025). "Furthermore, p130Cas, Crk, CrkL, and the p130Cas-Crk/CrkL complex play a significant role in tumor-specific cellular functions, such as cell transformation, migration, and invasion, as elaborated upon in the subsequent discussion." (PMID 40362257, 2025). "Moreover, we evaluated the expression of tsRNA-07804 and CRKL in tumor tissues and adjacent tissues from patients with NSCLC (n = 16)." (PMID 38289488, 2024). "This suggested that CRK may exert tumor-suppressive functions while CRKL may act as a pro-tumorigenic factor." (PMID 39126118, 2024). "Previous studies demonstrated that overexpression of CRKL enhances tumor cell functions, such as proliferation, invasion, migration, epithelial mesenchymal transformation, cell growth, and metastasis, which correlated with poor prognosis in many types of human cancers." (PMID 36653904, 2023). "MiR-124-3p, a tumor-suppressive miRNA that targets CRKL, suppresses HCC carcinogenesis." (PMID 36314741, 2022). "In addition to suppressing tumor growth at the primary injection sites in nude mice, Crk or CrkL knockdown reduced metastatic tumor burden." (PMID 33801580, 2021). "Thus, impedance-based, real-time measurement of tumor cell migration represents a robust assay for monitoring Crk and CrkL activities." (PMID 33561443, 2021). "Conversely, overexpression of tumor cells with Crk or CrkL enhances tumor cell functions." (PMID 33801580, 2021). "As a matter of fact, CRKL inhibitor PF‐114 has recently reported to induce tumour cell apoptosis." (PMID 34076957, 2021). "Therefore, it is necessary to carefully examine differential effects of Crk and CrkL inhibitors between tumor cells and normal cells to assess potential side effects by Crk/CrkL-targeted therapies." (PMID 33801580, 2021). "Although genetic manipulations such as gene knockout, knockdown, or overexpression helped uncover the contribution of Crk and CrkL to various tumor cell functions in vitro and in vivo, there is a significant challenge in using the genetic manipulations as therapy tools." (PMID 33801580, 2021).
tumor (continued). "We found CRKL expression was up‐regulated in HCC tumour tissues by IHC and WB assays." (PMID 33523562, 2021). "Previous studies have described the role of miR-200 family members, including miR-200a, miR-200b, miR-200c, and miR-429-3p in the regulation of expression of the E-cadherin transcriptional repressors ZEB1, ZEB2, and CRKL previously implicated in EMT and tumor metastasis." (PMID 33692799, 2021). "We hypothesize that the increased gene copy number triggers gene overexpression and elevated accumulation of CRKL protein in the nucleus, which in turn enhances cell proliferation and tumor development." (PMID 31913340, 2020). "Hence, our current work establishes a tumor promoter role for CRKL in hepatocarcinoma progression and hepatocarcinoma cells aggressiveness." (PMID 32326970, 2020). "Together these findings suggest that CRKL may be a potential target for novel anti-cancer therapies in a subpopulation of patients which show a tumor specific amplification/overexpression of this gene." (PMID 31913340, 2020). "Taken together, our results indicated that ETV6, CRKL might act as tumor promoters and miR-429 as a tumor suppressor involved in the development and progression of HCC." (PMID 32326970, 2020). "Moreover, functional analyses suggest that proliferation and migration of the tumor cells depend on CRKL expression." (PMID 31913340, 2020). "miR-379 might act as a tumor suppressor in CC via negatively modulating V-crk avian sarcoma virus CT10 oncogene homolog-like (CRKL)." (PMID 30833362, 2019). "Additionally, several non-receptor kinases and phosphatases such as PRKCD, PPP1R11, CRKL and PTPRA4 were identified for the first time as implicated in the crosstalk between CAFs and tumor epithelial cells." (PMID 29946230, 2018). "CRKL was a functional effector of miR-429 mediated anti-tumor effect." (PMID 29403024, 2018). "Adhesion is an important step in tumor metastasis, miR-429 overespression inhibited the in situ lymph node and extracellular matrix FN adhesion potentials, consistently, CRKL knockdown also inhibited the in situ lymph node and extracellular matrix FN adhesion potential." (PMID 29403024, 2018). "Furthermore, patients co-expressing GAB/CRKL/FRS2 in the tumor had a significantly worse outcome than those with single marker expression." (PMID 28558797, 2017). "Knockdown of either ALK or CRKL in this primary tumor line also inhibited cell viability." (PMID 27078848, 2016). "We demonstrate that CRKL serves as an adaptor molecule to facilitate focal adhesion formation, mediates outside-in signaling through Itgβ1 to drive cell invasion, and inside-out signaling that maintains tumor cell-matrix contacts required for cell invasion." (PMID 26728244, 2016). "In tumor specimens, 70.8% (51/72) of the cases showed ‘high expression’ of CRKL, and in non-cancerous tissues, only 12.5% (9/72) of the cases showed high CRKL expression, which was consistent with our previous finding that CRKL frequently expresses higher in GC tumor tissues." (PMID 27846244, 2016). "Additionally, across the TCGA datasets (n = 9105 tumor specimens), CRKL levels negatively correlated with the miR-200 family levels, positively correlated with the expression of ZEB1, an EMT gene expression signature, and the p-Src Y416 levels." (PMID 26728244, 2016). "Similarly, most of the tumor tissues expressed in high level for both CRKL and SLC7A5, which is consistent with the result discovered in GC cell lines." (PMID 27846244, 2016). "It is unclear whether Crk/CrkL-dependent tumor cell migration and invasion also depend on p130Cas." (PMID 40362257, 2025). "However, it is unclear whether Crk and CrkL make distinct or overlapping contributions to tumor cell functions in various cancer types because Crk or CrkL have been examined independently in most studies." (PMID 33801580, 2021).
tumor (continued). "Therefore, it is less clear whether Crk or CrkL alone is involved in tumor cell functions and whether both proteins play overlapping or distinct roles in each cancer type." (PMID 33801580, 2021). "In an in vivo GvHD/GVT model, CrkL deficient T cells failed to traffic to GvHD target organs and did not cause inflammation, but could efficiently clear hematopoietic tumor cells." (PMID 32391120, 2020). "Furthermore, gene knockdown and knockout of Crk and CrkL in tumor cell lines suppress tumor cell functions, including cell proliferation, transformation, migration, invasion, epithelial-mesenchymal transition, resistance to chemotherapy drugs, and in vivo tumor growth and metastasis." (PMID 33801580, 2021). "After, we observed a significant positive correlation between the expression levels of ETV6 and CRKL in hepatocarcinoma tumor tissues and hepatocarcinoma cell lines, then we investigated the mutual influence between the dysexpression of ETV6 and CRKL." (PMID 32326970, 2020). "A tissue microarray composed of 48 paired tumorous and adjacent normal tissues from HCC patients was further employed to address the expression alteration of CRKL by IHC." (PMID 32326970, 2020). "V-crk sarcoma virus CT10 oncogene homolog (avian)-like (CRKL) is a CRK adapter protein family member, transversely expressed in eukaryotic organisms and contributes in tumor growth and invasion." (PMID 33094104, 2020). "We found that ETV6 and CRKL were upregulated, and miR-429 was downregulated in HCC patients’ tissues and HCC cell lines compared with corresponding non-tumor liver tissues and a normal liver cell line." (PMID 32326970, 2020). "CRKL, ETV6 acts as tumor promotors and miR-429 acts as a tumor suppressor in HCC, their dysexpressions are involved in the carcinogenesis and progression of hepatocarcinoma." (PMID 32326970, 2020). "The positive rates in tumor regions for GAB2, CRKL, and FRS2 were 40.00% (30/75), 53.95% (41/76), and 35.06% (27/77), respectively." (PMID 28558797, 2017). "Staining patterns of anti-GAB2 and anti-CRKL antibodies were both cytoplasmic and nuclear in the tumor regions, while that of the anti-FRS2 antibody was cytoplasmic and membranous in the tumor regions." (PMID 28558797, 2017). "Zeb1-dependent EMT enhances tumor cell responsiveness to the ECM composition and activates FAK/Src pathway signaling by de-repression of the direct miR-200 target, CRKL." (PMID 26728244, 2016). "Analysis of the expression of both CRKL and SLC7A5 in 72 tumor specimens by IHC was conducted, compared with the adjacent non-cancerous tissues." (PMID 27846244, 2016). "Biochemically, the increased matrix responsiveness of tumor cells upon Zeb1 expression was due to enhanced FAK signaling, which was essentially shutoff with high miR-200 levels and phenocopied by CRKL or Itgβ1 knockdown." (PMID 26728244, 2016). "Importantly, within the high grade basal tumors in both TMA datasets, CrkI/II and CrkL protein levels correlated with proliferation, as assessed using Kendall's tau non-parametric statistical analysis, demonstrating a strong link between elevated Crk protein and an aggressive tumor phenotype." (PMID 22569336, 2012). "Also, miR-429 appears to play a role in the suppression of tumor proliferation by targeting the ZEB1 and CrkL signaling pathways." (PMID 40362257, 2025). "TNMplot data analysis results showed that CRKL was remarkably upregulated in tumor tissues of LUSC patients compared with non-tumor tissues." (PMID 38289488, 2024). "CRKL is an oncogenic adaptor protein containing SH2 and SH3 domains that controls cell proliferation, cell adhesion, cell metastasis, EMT, and tumor formation." (PMID 37894400, 2023). "CRKL regulates cell proliferation, cell adhesion, cell metastasis, EMT, and tumor formation." (PMID 37894400, 2023). "If so, one would predict that if the tumor were located in a peripheral tissue outside of the lymphatic system, CrkL KO T cells would not be able to access and kill the tumor." (PMID 32391120, 2020).